INS (insulin)
Diseases named in the same sentence as INS in open-access papers (continued):
Sharing a sentence is not in itself a finding about the gene and the disease.
diabetes (continued). "Short-acting insulin-release stimulants are used to treat diabetes." (PMID 37746464, 2023). "One of the main hypotheses involves the overproduction of insulin, characteristic of patients with diabetes, and the corresponding stimulation of the phosphatidylinositol-3-kinase/Akt/mammalian target of rapamycin (PI3K/Akt/mTOR) pathway." (PMID 36677437, 2023). "Pre-diabetes and T2D are strongly associated with obesity, but all fat depots are not created equal, exhibiting various profiles of insulin sensitivity, lipolytic and secretory activity." (PMID 36709226, 2023). "In addition, SGLT2 inhibitors exhibit an insulin-independent mode of action, rendering them suitable for use in patients with varying degrees of insulin resistance and type 2 diabetes mellitus (T2DM)." (PMID 37908957, 2023). "For instance, discrepancies between studies regarding the inclusion or exclusion of patients with diabetes or varying degrees of insulin resistance may impact observations of the overall effect of GHRT on long-term insulin sensitivity." (PMID 36380045, 2023). "Future studies will continue to explore the contribution of Golgi function to proinsulin trafficking and whether defects in Golgi protein sorting and export contribute to impaired insulin secretion in both major forms of diabetes." (PMID 36997560, 2023). "In conclusion, in patients without apparent diabetes, napping for a long period of time was found to be independently associated with decreased insulin sensitivity from autonomic dysfunction." (PMID 38027100, 2023). "Lower LDL-cholesterol subgroup also reflected higher proportion of pre-existing comorbidities of hypertension, and long-standing diabetes mellitus (more than 5 years), as well as prior medication of statin, multiple oral hypoglycemic agents (three or more), and insulin." (PMID 36803488, 2023). "Diabetes mellitus is a group of endocrine diseases conjugated with impaired glucose uptake owing to absolute or relative (violation of interaction with target cells) insufficiency of the hormone insulin." (PMID 38138613, 2023). "Interestingly, members of the miRNA-30 family have been reported to affect beta-cell insulin production, apoptosis and transdifferentiation to alpha-cells, and to function as biomarkers for pre-diabetes." (PMID 36761184, 2023). "In the literature, an increase in the incidence of diabetes has been reported in patients with OSA, but PAP device therapy does not appear to be associated with this risk, although it has been reported that CPAP improves the HOMA insulin resistance index." (PMID 37048530, 2023). "Type 2 diabetes mellitus is non-insulin-dependent and is otherwise determined as adult diabetes." (PMID 36832207, 2023). "However, these complications tend to be less frequent and severe in comparison to other types of diabetes, primarily due to the persistent presence of minimal endogenous insulin secretion." (PMID 38136081, 2023). "Therefore, there is a need for validation of the role of this metagenome through deciphering of the genome-to-phenome trajectory of diabetes using replication studies in different insulin-responsive tissues." (PMID 36979367, 2023). "This study focuses on insulin/insulin analogue prescriptions used to treat diabetes in childhood." (PMID 36869270, 2023). "Type 2 diabetes mellitus is non-insulin-dependent diabetes; in this condition, insulin is secreted by pancreatic β cells, but insulin resistance occurs in the body, causing a decrease in insulin secretion or a breakdown in the insulin response system." (PMID 37111730, 2023). "These discrepancies between studies may be due to differences in baseline insulin sensitivity (patients with insulin resistance respond better to chromium), quantity of chromium administered, study period, sample size, and type of diabetes mellitus." (PMID 38024820, 2023).
diabetes (continued). "Taken together, these findings suggest that a slow decline in insulin secretion over a period of 5 years, coupled with a modest increase in insulin resistance and low insulin secretion at baseline, may lead to the development of diabetes." (PMID 36769457, 2023). "This explains why the dwAG or A-GTT curve may be a better indicator of transitioning to type 2 diabetes mellitus or future cardiovascular disease and mortality than low insulin sensitivity alone." (PMID 36967663, 2023). "Thus, dysfunction to the insulin signaling pathway, such as the disruption in patients with diabetes mellitus, alters the function of Kv1.3 and leads to olfactory dysregulation." (PMID 37345053, 2023). "The recent failure of metformin to improve metabolic control of obese adolescents with T1DM diabetes illustrates a continuing unmet need for an adjunctive therapy like DDP-4 inhibitors that could reduce insulin requirements in type 1 diabetes." (PMID 38057844, 2023). "We note that associations with lower insulin secretion when not corrected for insulin sensitivity are consistent with a protective effect - because, in people without diabetes, a higher insulin sensitivity results in reduced need for insulin secretion." (PMID 36798216, 2023). "Diabetes mellitus is defined and diagnosed as a presence of high serum concentrations of glucose due to dysregulated insulin secretion and/or insulin sensitivity and can be classified according to different pathophysiology processes, with different therapeutic management solutions." (PMID 36834796, 2023). "Diabetes is a chronic metabolic syndrome, which is characterized by the cells becoming resistant to insulin or by the inability of the pancreas to secrete sufficient insulin levels." (PMID 36677933, 2023). "On 11 January 1922, the first patient with diabetes received insulin, prompting a dramatic revolution in the treatment and prolongation of the lifespan of diabetic patients and more pronounced manifestations of late diabetic complications, with angiopathy as a common denominator." (PMID 37569392, 2023). "These abnormalities arise due to either a significant or complete lack of insulin, which is caused by the autoimmune destruction of the pancreatic beta cells responsible for insulin production (known as type 1 diabetes or insulin-dependent diabetes mellitus)." (PMID 38132485, 2023). "Concretely, in diabetes patients, hyperglycemia, insulin resistance and altered insulin signaling, neuroinflammation, cerebral microvascular injury, and accumulation of cerebral amyloid and tau proteins are among the postulated pathophysiological mechanisms underlying cognitive decline." (PMID 37513524, 2023). "Diabetes mellitus is a chronic metabolic disorder characterized by elevated blood glucose levels resulting from the inability of the body to produce or effectively use insulin." (PMID 37313065, 2023). "However, if a child has been diagnosed with diabetes requiring insulin therapy, then that child will use insulin for the rest of his/her life, and these prescriptions are issued in primary care." (PMID 36869270, 2023). "Patients in the second cohort presented a higher prevalence of diabetes-related conditions, insulin usage, and a greater number of diabetic medications taken, indicating a generally more severe diabetic profile compared with the first cohort (eTable 1 in Supplement 1)." (PMID 37751205, 2023). "For example, a device that continuously measures blood glucose levels and autonomously releases insulin when needed could revolutionize diabetes management." (PMID 37688233, 2023). "“Real-time continuous glucose monitoring should be offered for diabetes management in adults with diabetes on multiple daily injections or continuous subcutaneous insulin infusion who are capable of using the devices safely,” supported by randomized controlled trials with a level of evidence A." (PMID 37711232, 2023). "Its expression in diabetes is elevated in response to increased insulin levels." (PMID 36978843, 2023).
diabetes (continued). "Traditional diabetes medications predominantly target insulin secretion or insulin sensitivity." (PMID 37908957, 2023). "This work highlights the beneficial effect on diabetes through different mechanisms of action, namely, decreasing digestive enzyme activities, translocation of glucose transporter 4 into cells, and activation of insulin and the AMPK-signaling pathway." (PMID 37432337, 2023). "Differentiating between type of diabetes (insulin dependent and not insulin dependent), COVID-19 was associated only with non–insulin-dependent disease." (PMID 37071420, 2023). "Moreover, diabetes can involve dysfunction of the pancreas itself or other insulin-responsive tissues (e.g., liver, muscle, and/or fat)." (PMID 38229904, 2023). "These pools of insulin granules were absent in T2DM donors and INS-1 cells mimicking diabetes, implicating the role of these Ca2+-triggered granules in the loss of rapid first-phase insulin secretion seen in T2DM patients." (PMID 37371672, 2023). "Functional insulin signaling is necessary to maintain normal energy metabolism and biochemical reactions in the body; however, disturbances in insulin signaling such as insulin resistance are partly responsible for diabetes mellitus, metabolic syndrome and cardiovascular diseases." (PMID 37884540, 2023). "In this study, we address hepatic proteome and metabolome alterations alongside clinical-chemical changes and histomorphological findings in piglets developed in genetically hyperglycemic INSC94Y transgenic pigs, a model for mutant INS gene induced diabetes of youth (MIDY)." (PMID 37414142, 2023). "Feeding zebrafish with 10% cholesterol and immersing them in a 2% glucose solution simultaneously for 19 days resulted in more symptoms of diabetes in zebrafish larvae, such as significant increases in insulin, glucagon, glucose, triglyceride, and cholesterol levels." (PMID 37569372, 2023). "Higher age, BMI, and proportion of diabetes family history were also characteristics of patients with preoperative long-duration diabetes, which could help determine whether patients have greater insulin requirements." (PMID 36860372, 2023). "Interestingly, we also found that the incidence rate and adjusted HR for newly developed diabetes cases requiring insulin treatment in the cancer group were significantly higher than those in the non-cancer group." (PMID 36831436, 2023). "The variables most consistently linked to the development of DR in diabetic patients include increased fasting blood sugar levels, prolonged duration of diabetes, obesity, hypertension, being on insulin therapy exclusively, history of diabetes in relatives, and low socioeconomic position." (PMID 37090386, 2023). "The first therapeutic protein ever used was insulin for the treatment of diabetes mellitus." (PMID 36678915, 2023). "Treatments with statins for hyperlipidemia and with pioglitazone, acarbose, and insulin for diabetes have been reported to reduce the serum electronegative LDL-C levels through their effects that cause LDL-C modification, decreased systemic inflammation, and glycemic optimization." (PMID 36836428, 2023). "While this study showed a 10.1% prevalence of postpartum prediabetes among all GDM patients, remarkably higher figures of glucose intolerance (60%) were noted in another study from Saudi Arabia, with a family history of diabetes and insulin treatment of GDM being the main predictors." (PMID 37680834, 2023). "It is noted that the pathophysiological progression of T2DM begins with normal glucose tolerance, transitions to impaired glucose tolerance, and ultimately culminates in overt diabetes due to the concomitant decline in both insulin sensitivity and beta‐cell function." (PMID 37915365, 2023).
diabetes (continued). "Model simulation with the new function C(I, X) shows that the insulin sensitivity decreases before the onset of diabetes, then increases slightly for a while due to diminished insulin-induced resistance, and then goes back to the decreasing trend with the progression of obesity." (PMID 36848379, 2023). "However, the intrinsic mechanism underlying the reduction in the number of β-cells or the impairment of insulin secretion in diabetes remains largely unclear." (PMID 37195917, 2023). "Several insulin delivery systems are available to control glycemia in patients with diabetes." (PMID 36828942, 2023). "Insulin mimetics with agonistic or antagonistic effects toward the receptor could find applications in treating diabetes or malignant diseases." (PMID 36633503, 2023). "However, in an individual with diabetes, the pancreas either cannot produce sufficient insulin or the body loses its ability to use the insulin produced." (PMID 37370893, 2023). "Dexamethasone diabetes models (glucose tolerance, oral rapid insulin, and adrenalin tests) were used to determine the specific hypoglycemic activity, and compound 48 (R=H) revealed high activity, exceeding the reference drugs metformin 1 and gliclazide on White Wistar rats." (PMID 38139019, 2023). "Thus, the increase of Wnt4 in individuals with diabetes can indirectly affect the osteogenesis process by affecting insulin synthesis." (PMID 37106471, 2023). "A bidirectional relationship between melatonin levels and insulin secretion may explain our findings in patients with diabetes." (PMID 36959654, 2023). "○ Regimen used (insulin administration and glucose monitoring); adjustments to basal rates/background and insulin-to-carbohydrate ratios; dietary choices and managing diabetes at mealtimes; undertaking physical activity; attainment of pregnancy glucose targets." (PMID 37795883, 2023). "Individuals with diabetes had significantly higher levels of 2-AAA (ion count 312x104 ± 75x104) than both the insulin sensitive (ion count 233x104 ± 60x104, P<0.001) and the pre-diabetic (ion count 262x104 ± 58x104, P=0.005) groups in models adjusted for sex, race, BMI and smoking status." (PMID 37745703, 2023). "Beyond insulin, other medications given for diabetes can also influence iron metabolism." (PMID 37029208, 2023). "High blood glucose levels are a symptom of diabetes mellitus (DM), which is caused by an absolute or relative lack of insulin production and/or insulin resistance." (PMID 37842332, 2023). "All data were anonymous; therefore, patients’ characteristics that could possibly influence final outcomes such as age, duration of diabetes, type of insulin therapy, and dietary habits, as well as exercise patterns, were unavailable." (PMID 38003943, 2023). "Nevertheless, the extended elevation of insulin levels may lead to the depletion of pancreatic beta cells, ultimately contributing to the onset of diabetes." (PMID 37868469, 2023). "Later, in 2008, the PERISCOPE (Pioglitazone Effect on Regression of Intravascular Sonographic Coronary Obstruction Prospective Evaluation) trial compared the effects of pioglitazone and glimepiride (an antidiabetic Insulin secretagogue) in 543 patients with diabetes mellitus and coronary disease." (PMID 36768666, 2023). "Likewise, both the “Maturity onset diabetes of the young” and “Insulin secretion” pathways are exclusively enriched in AA-SScL fibroblasts." (PMID 36835058, 2023). "Attenuated insulin release from β-cells represents one of the major contributors to diabetes." (PMID 37195917, 2023). "In diabetes monitoring and therapy, important cues have to be further explored, and thus advanced hydrogels are being developed to monitor high glucose levels, release insulin, or encapsulate pancreatic cells." (PMID 37298999, 2023).
diabetes (continued). "Indeed, ARASCO oil, which was identified as a source of AA, diminished hyperglycemia, restored insulin sensitivity, suppressed inflammation and reversed the altered antioxidant status in streptozotocin-induced diabetes mellitus." (PMID 37298790, 2023). "The mean fasting C-peptide level was 1.2 ± 0.9 nmol/l and 12.3% of the participants had C-peptide < 0.26 nmol/l.***More than half of the participants had high C-peptide levels suggesting significant endogenous insulin secretion (C-peptide was measured 1 week from diabetes diagnosis)." (PMID 36778553, 2023). "Besides, increased levels of these cytokines further alter insulin sensitivity through direct and indirect mechanisms, resulting in a vicious cycle between diabetes progression and periodontal damage." (PMID 38149100, 2023). "The common treatment options for diabetes in Iran include calorie restrictions, diet control, lifestyle management, regular exercise training, oral glucose-lowering medications, monotherapy with insulin administration, and combination therapy with insulin." (PMID 37542207, 2023). "Second, although patients tend to perceive and experience higher diabetes distress and stigma due to the need for lifelong insulin treatment, patients with type 2 diabetes also frequently feel discriminated against and shamed because of their weight and dietary habits." (PMID 37620853, 2023). "So, if the levels of Acrp30 will be increased in the circulation then the insulin sensitivity can be increased and blood glucose levels can be easily managed which will make Acrp30 a potential novel target for the treatment of diabetes mellitus." (PMID 36782201, 2023). "Another characteristic feature of type 1 diabetes mellitus is inappropriately low levels of insulin and C-peptide relative to plasma glucose concentrations, while high levels of fasting insulin and C-peptide point toward a diagnosis of type 2 diabetes mellitus." (PMID 36979685, 2023). "However, increasing evidence suggests that an improvement of first-phase insulin secretion as a signal of improved β-cell function contributes to a long-term clinical benefit of weight reduction and diabetes control." (PMID 39872624, 2023). "Diabetes is a chronic metabolic disease characterized by an insufficient amount of insulin due to pancreatic beta cell destruction (type 1 diabetes) or cell inability to effectively use insulin due to impaired responsiveness (type 2 diabetes)." (PMID 36770924, 2023). "Amelioration of insulin dependency has been reported in an adolescent treated with HSCT 1 month after diabetes onset, suggesting the period from onset may also impact efficacy." (PMID 36600150, 2023). "However, there is limited evidence confirming the role of polyphenols from nuts in glycemic control, insulin sensitivity, and ultimately in the prevention and management of diabetes." (PMID 36839236, 2023). "Patients with diabetes are vulnerable to postoperative hypoglycemia due to surgical stress, impaired renal function, older age, anesthesia, postoperative fasting, and improper use of insulin." (PMID 37675290, 2023). "The identification of IBOA as the major contact allergen in diabetes medical devices was the praeludium to further research of other allergens that might be present in glucose sensors and insulin infusion sets." (PMID 37445875, 2023). "Exclusion criteria, especially use of GLP‐1 analogues and insulin, and proliferative retinopathy, may have led to selection of participants with longstanding diabetes with lean phenotype, an acceptable HbA1c and overall few microvascular complications." (PMID 38059537, 2023). "Adolescents should be empowered, by attending the SEP, to feel more confident in deciding their own insulin doses accurately and taking gradual care of their diabetes, under the supervision and support of their parents and the dietician, in preparation for transition later on into adult life." (PMID 40303263, 2023).